LAG3 (lymphocyte activating 3)
Diseases named in the same sentence as LAG3 in open-access papers (continued):
Sharing a sentence is not in itself a finding about the gene and the disease.
tumor (continued). "Moreover, the positive correlations between CCDC137 expression and immunosuppressive genes, such as TGFB1, NECTIN2, LGALS9, LAG3, and IL10RB, indicate the key role of CCDC137 in regulating tumor immunology, macrophage polarization, and CAFs formation." (PMID 34055889, 2021). "Third, the expression of other immune molecules should be detected together with the LAG-3 and PD-L1 to better understand the mechanism of TACE therapy affecting tumor immunity, so as to provide theoretical basis for the combination of TACE and immunotherapy in HCC patients." (PMID 34691076, 2021). "Protein expression comparisons of immune and tumor cells reveal that PD-L1 was predominantly expressed on tumor cells, while ICOS, IDO-1, LAG-3, and OX40 were predominantly present on immune cells, and TIM-3 and VISTA were expressed on both tumor and immune cells in similar proportions." (PMID 34093591, 2021). "Similar to prior results, the mean value of LAG3 (p = 0.004) and HLA-DR (p = 0.004) was higher in M3 than in D3 tumours; this was not the case for Galectin-3 (p = 0.61)." (PMID 34503258, 2021). "Likewise, LAG-3 is overexpressed on TILs of HNSCC patients, and its expression correlates with high pathological grade, tumor size, and worse prognosis." (PMID 33804419, 2021). "The discrimination of LAG-3, TIM-3, and TIGIT profiles in tumours may have a broad impact on investigations of immunotherapy responses after targeting a new series of IRs." (PMID 34545095, 2021). "Tumor cells mediate immunosuppression taking over inhibitory checkpoint proteins such as PD-1, T cell immunoglobulin and mucin domain 3 (TIM-3), lymphocyte activation gene 3 (LAG-3), and CTLA-4 expressed on the surface of T lymphocytes." (PMID 34575678, 2021). "As seen in the tumor, we found no change in Treg proliferation, as measured by Ki67, and no change in activation/exhaustion markers PD-1 and LAG3." (PMID 33483333, 2021). "We developed a pH-responsive hybrid biomimetic membrane-camouflaged PLGA nanoparticle system based on multiple tumor targets and low-pH-activated endosomal/lysosomal escape to co-deliver the FGL1/LAG3 blockade molecule, siFGL1, and immuno-metabolic adjuvant Met." (PMID 33632231, 2021). "In the absence of such an increased ratio, tumours remained resistant to subsequent therapy with anti-LAG3." (PMID 33824480, 2021). "The research potential of LAG3/FGL1 is enormous, understanding more about them may result in a broader implication, which may provide a novel strategy for tumor therapy." (PMID 35111155, 2021). "We found that monotherapy with an immune checkpoint blocking antibody against programmed death-1 (PD-1), and its combination with another blocking antibody against lymphocyte activation gene-3 (LAG-3), resulted in delayed tumor growth and survival benefit in our mice." (PMID 33466653, 2021). "Galectin-3 and LAG-3 bind together to suppress CD8+ T cells, assisting tumour immune evasion." (PMID 34968365, 2021). "CD4+ naive T cells (cluster 0 and cluster 2) at the core of the tumor express more immune checkpoint molecules, such as CTLA4, which has been used in clinical practice, and LAG3, HAVCR2, and TNFRSF9/CD137, which are currently undergoing clinical trials than those at other locations." (PMID 34513820, 2021). "We next assessed whether blockade of LAG-3 and PD-1 in the MC38 model prolonged the tumor growth delay." (PMID 33712537, 2021). "Furthermore, it highlights a robust expression of MHC-II, the ligand of the immune checkpoint LAG-3, by the MSI-H tumor cells." (PMID 32641473, 2020). "LAG3 has been shown to play a crucial role in the negative regulation of T cells under physiological conditions and, importantly, in tumor cell - immune cell interactions, thus making it an attractive additional target in immunotherapy." (PMID 32861198, 2020). "It was found that the anti-tumor effect of anti-FGL1 monoclonal antibody depended on LAG-3 and anti-LAG-3 depended on FGL1 rather than MHC-II or other ligands." (PMID 33344447, 2020).
tumor (continued). "Interestingly, CRC patients display Treg cells with a higher expression of several molecules that correlate with suppression, such as Tim-3, LAG-3, TGF-β, IL-10, CD25, and CTLA-4, and by the BLIMP-1 transcription factor expression in the tumor." (PMID 32674255, 2020). "In the tumor microenvironment, exhausted T-cells are determined by impaired functional activities like cytokines secretion and up-regulation of co-inhibitory molecules, including CTLA-4, PD-1, Tim-3, and LAG-3." (PMID 32986360, 2020). "Tr1 lymphocytes have been detected in both tumor tissue and peripheral blood of EBV+ cHL patients, and configure a regulatory subset lacking Foxp3, but usually expressing integrin subunit alpha 2 (ITGA2) and lymphocyte-activation gene 3 (LAG3)." (PMID 33327433, 2020). "Several immunosuppressive mechanisms may be involved in the process, such as overrepresentation of immunosuppressive cells (e.g., Tregs) and increased expression of immunosuppressive molecules (e.g., PD-1, CTLA-4, LAG3, and CD47) in the tumor microenvironment." (PMID 32028264, 2020). "The HBV infection–related HCC immunosuppressed tumor microenvironment features upregulation of PD-1 in CD8+ T cells; long-lasting inhibition of Tregs via higher levels of IL-10 and TGF-β secretion; and the co-inhibitory signal of LAG3, TIM-3, and CTLA-4." (PMID 32547550, 2020). "The authors then performed a dual blockade of LAG-3 and CTLA-4 in PD-1 knockout mice, which resulted in an increase in tumor free survival to 40% of mice, as well as an increase of peritoneal CD8+ T cells and cytokine producing effector T cells, and a decrease in Tregs and MDCS." (PMID 32756436, 2020). "Notably, higher expression of PD-1 and lymphocyte-activation gene 3 (LAG3), as well as lower expression of CD28 and CD127, were commonly found in tumor-infiltrating CD8+ T cells of HBV-related HCC patients." (PMID 32547550, 2020). "In a multivariate cox-regression model, LAG3 expression alone failed to serve as an independent prognostic marker due its correlation with advanced tumour stages." (PMID 32592066, 2020). "Indeed, several immune checkpoints, such as T cell immunoglobulin 3 (TIM3), lymphocyte activation gene 3 (LAG3), or T cell immunoglobulin and ITIM domain (TIGIT), are potential regulators contributing to the immunosuppressive tumor microenvironment in RCC." (PMID 32709062, 2020). "By profiling the immune modulators, we found that some suppressors, including B7‐H3, LAG3, VEGFB and Siglec‐15, are significantly upregulated in tumor tissues, which may contribute to the relatively suppressive immune microenvironment in SCCE." (PMID 33033616, 2020). "For example, expression of PD-1, TIM-3, LAG-3, and CTLA4 is significantly higher on CD8+ and CD4+ T-cells in HCC tissue than those in non-tumor tissues or peripheral blood, and dendric cells (DCs), monocytes, and B cells in tumors express ligands for these receptors." (PMID 32443599, 2020). "We also found that CTLA4 and IDO1, two well‐known immune checkpoints, were significantly higher in both tumor tissues and NATs than in healthy tissues, while the expression levels of VEGFB and LAG3 increased progressively in healthy tissues, NATs and tumor tissues." (PMID 33033616, 2020). "A linear relationship was also evident for LAG3 and FCRL6 with the degree of HLA-DR+ tumor cells." (PMID 33162991, 2020). "In pre-clinical cancer models, Lag-3 expression has been found to be co-expressed with PD-1 on tumor-infiltrating CD4+ and CD8+ T cells and co-blockade of Lag-3 and PD-1 can improve the proliferation and cytokine production of tumor-antigen specific CD8+ T cells." (PMID 33101304, 2020). "Combination treatment with mAbs against both negative receptors significantly reduced tumor growth in mouse models that were unresponsive to monotherapy mAb treatment, which indicates synergy between the PD-1 and LAG-3 inhibitory pathways." (PMID 33304346, 2020).
tumor (continued). "We speculate that RNF183, which is highly expressed in the tumor microenvironment, leads to a better prognosis of UCEC by regulating the expression of inhibitory immune checkpoint proteins PD-1, LAG3 and GZMB on exhausted T cells." (PMID 33324448, 2020). "The co-blockade of CTLA-4 and LAG-3 or PD-1 and LAG-3 showed better therapeutic efficacy through increased CD8+T cells with/without the reduction of Tregs in the tumor, compared to single CTLA-4 or PD-1 targeting." (PMID 32508809, 2020). "Targeting tumor-specific T cells, therapeutic interceptions that inhibit receptors, including PD1 (pembrolizumab, nivolumab), CTLA4 (ipilimumab, tremelimumab) and LAG3 (BMS-986,016), have been approved or are in clinical trials for the treatment of various cancer types." (PMID 33228738, 2020). "LAG-3 is a negative co-inhibitory receptor mainly expressed on T and NK cells, but also on other immune cells including tumor infiltrating lymphocytes (TILs), Treg, iNKT cells, B cells, and DCs." (PMID 33255582, 2020). "On the other hand, systemic therapy with mCelyvir resulted in non-significant increased mean values of CD8 and CD4 T lymphocytes per tumor volume, expressing markers of recent and sustained T cell activation (OX40 among CD8, PD1 and LAG3 among both CD4 and CD8, and TIM3 among CD4)." (PMID 32064039, 2020). "This might be explained by the fact that LAG-3 is expressed on activated immune cells, such as CD8+ T cells, and therefore might reflect infiltration of the tumor and initial tumor control by these immune cells." (PMID 33374804, 2020). "The co-expression of PD1, CTLA4, LAG3, and TIM3 were more commonly observed in tumor tissues compared with normal tissues, which may explain the limited effects of a single immune checkpoint inhibitor and the use of combined strategies." (PMID 32728493, 2020). "Furthermore, VEGF-A induces the upregulation of multiple immune checkpoints, such as PD-1, CTLA4, TIM3 and LAG3, in tumor-infiltrating CD8+ T cells, and VEGF-silencing potentiates tumor control mediated by the PD-1 blockade." (PMID 32231117, 2020). "LAG3 is an alternative inhibitory receptor target showing promising activity; CD137 is a member of the tumor necrosis factor receptor family increasing antitumor response by altering the tumor microenvironment." (PMID 33375286, 2020). "More importantly, this study showed that tumor-infiltrating immune cells express the checkpoint marker LAG3 rather than PD1 or CTLA4." (PMID 33585560, 2020). "Inhibition of PD-L1, LAG3, and CTLA4 could increase CD8 T cells and CD4 T cells and reduce Tregs, thereby enhancing anti-tumor response." (PMID 33401247, 2020). "LAG3 belongs to the immunoglobulin superfamily (IgSF) and is particularly displayed on several forms of T-lymphocytes (CD4+, CD8+, regulatory T-cells [Treg], tumour infiltrating lymphocytes [TILs]), as well as B-lymphocytes and dendritic cells." (PMID 32592066, 2020). "It should be noted however that, when tumor rejection was seen in the absence of IL-35, achieved by Ebi3 KO in the tumor host, tumor-infiltrating T cells no longer expressed LAG3 and TIM3, but still expressed PD1, a common activation marker of T helper cells." (PMID 32983104, 2020). "This lack of response may be due to the relatively low total number of CT26 resident cytotoxic T cells, despite tumour-infiltrating CD8+ cells having been shown to express TIM-3 and LAG-3." (PMID 32705455, 2020). "The localization of the CD4+Foxp3+ and CD4+LAG3+ T-cells remains instead more controversial, but it may be dictated by the expression of MHC-II on tumor cells." (PMID 33327433, 2020). "In tumor bearing mice, crizotinib increased the expression of the PD-1 (and LAG-3 but neither CTLA-4 nor TIM-3) on circulating CD4+ or CD8+ T lymphocytes." (PMID 30940805, 2019).
tumor (continued). "Importantly, EGFR-expressing OT-1 T cells injected into B16-OVA tumor bearing mice were recruited into the tumor, expressed lower levels of the exhaustion markers PD1, TIGIT, and LAG3, and were more efficient in delaying tumor growth." (PMID 31921216, 2019). "The anti-tumor efficacy of anti-mouse LAG-3 antibodies without effector functions was also observed by other groups." (PMID 30863404, 2019). "Our results showed that combining α-PD-1 with α-CTLA-4 antibody, but not α-Lag3, resulted in significantly enhanced tumor-free survival relative to that of mice treated with either antibody alone." (PMID 31533840, 2019). "LAG3 principally interacts with major histocompatibility complex class II (MHC-II) molecules as its ligand, which is expressed on the surface of Ag presenting cells (APCs) and tumor cells." (PMID 31434339, 2019). "The OS tumours OS04 and OS03, and BZ28 and BZ35 that had the highest CD8A gene expression, also had high expression of PD-1, Tim-3, LAG-3 and CTLA4, indicative of a complex dysfunctional state of the CD8 + TILs in these tumours." (PMID 30674975, 2019). "Together, these results suggested that the triple downregulations of PD-1, Tim-3, and Lag-3 lead to the upregulation of CD56 and the enhanced infiltration of PTL-Her2-CAR-T cells in tumor tissue could be mediated by CD56." (PMID 31511513, 2019). "Pre-clinical evidence supports a rationale for combination therapy as, by blocking more than one of these pathways, including PD-1, LAG-3, and CTLA-4, may reduce tumor growth." (PMID 30941125, 2019). "At the end of study (i.e., 39 days post CAR-T cell injection), CAR-T cells isolated from liver THP1-FRβ tumor metastases of EC17 TIW-treated animals appeared to have the least expression of double- and triple-positive T cell inhibitory receptors, PD1, LAG3, and TIM3." (PMID 30941303, 2019). "LAG3 and PD-1 co-expression has been used to identify dysfunctional CD8+ T cells in human tumors with their co-blockade in ovarian cancer improving proliferation and cytokine production by tumor-Ag-specific CD8+ T cells." (PMID 31434339, 2019). "A variety of inhibitory and stimulatory receptors could co-express on tumor antigen-specific CD8+ T cells (including CD160, KLRG-1, TIM-3, 2B4, BTLA, and LAG3)." (PMID 31708918, 2019). "Furthermore, by using tumor-primed cytotoxic T cells and anti-TIM-3 and anti-LAG-3 compounds in in vitro experiments, we found evidence of increased anti-tumor activity against DLBCL cell lines following checkpoint blockade." (PMID 31007846, 2019). "Tumor-infiltrating CAR-T cells (liver metastases) from EC17 TIW treated cohorts also appeared to have the least expression of double- or triple-positive surface inhibitory receptors, PD1, LAG3, and TIM3." (PMID 30941303, 2019). "In addition, we evaluated the effects of investigational anti-PD-1, anti-LAG-3 and anti-TIM-3 antibodies in in vitro cytotoxic assays of tumor-primed T cells against DLBCL cell lines." (PMID 31007846, 2019). "Moreover, LAG3 is known to be expressed on the surface of CD4+ and CD8+ cells, implicating the possibility that the tumor-infiltrating lymphocytes (TILs) within immune-inflamed LUSCs of our study were in a more exhausted state than immune-inflamed LUADs." (PMID 30956762, 2019). "LAG-3 intracellular signaling and the specific mechanisms of immunosuppression still remain to be elucidated; however, immunosuppression is likely achieved through LAG-3: MHC II interaction resulting in impaired maturation of DCs, and anergy and arrest of tumor infiltrating T cell." (PMID 31681327, 2019). "Similarly, to TIGIT and LAG3, the high expression of TIM-3 and PD-1 is observed in the tumor microenvironment, in particular on TIL and Treg, suggesting the possible re-establishing of T cell function through the targeting of TIM-3 and PD-1." (PMID 30991686, 2019).
tumor (continued). "Through investigating the mechanism underlying the increased infiltration and antitumor activity of CAR-T cells in the tumor tissue, we demonstrated the significant amount of CD56 occurs on the CAR-T cells after the simultaneous decreased expression of PD-1, Tim-3, and Lag-3." (PMID 31511513, 2019). "These tumours were characterised by the presence of abundant regulatory CD4+ T cells and CD8+ T cells co-expressing several inhibitory receptors (e.g., PD-1, Tim-3 and Lag-3)." (PMID 30413828, 2019). "Accordingly, pharmacological blockade of C5aR1 in a syngeneic model of lung cancer impaired tumor growth, decreased the percentage of splenic MDSCs, and downregulated immunosuppression-related genes including ARG1, IL6, IL10, CTLA4, LAG3, and PDL1 within the tumor milieu." (PMID 31001273, 2019). "Their results showed that dual blockade of LAG-3 and PD-1 synergistically enhanced anti-tumor immunity and suppressed tumor growth by enhancing CD8+ tumor infiltrating T cells (TILs) and decreasing regulatory T cells (Tregs) in the tumor microenvironment (TME)." (PMID 31690319, 2019). "Since immunotherapy regimens most commonly employ monoclonal antibodies targeting regulatory checkpoints, we determined the expression levels of four immune checkpoints (CTLA4, LAG3, PD1, and TIM3) on tumor infiltrating T cells, and PD-L1 expression on B6CaP tumor cells." (PMID 31839878, 2019). "Binding to LAG3 expressing on CD8+T cells and NK cells, tumor cells could get the capacity to escape immune clearance." (PMID 31708918, 2019). "We found that PD-1, CTLA-4, TIM-3, and LAG-3 were upregulated in tumor tissue, compared with normal tissue, while there was no change in PD-L1 and TIGIT." (PMID 29983831, 2018). "Similarly, tumor-derived NY-ESO-192–100 CD8+ T cells isolated from ovarian cancer patients showed an upregulation of the inhibitory molecules PD-1 and LAG-3 with dual blockade enhancing the proliferation and cytokine production." (PMID 29770138, 2018). "Both LAG3 and TIM3 are frequently co-expressed with PD-1 on anergic or exhausted tumor-specific CD8+ T cell, and for this reason, escape from PD-1 pathway blockade could be achieved by additive expression of co-inhibitory receptors on CD8+ T cells." (PMID 29482595, 2018). "Intriguingly, blocking LAG3, TIM3, or TIGIT alone had a minimal impact on tumor growth inhibition, but was active only in combination with anti-PD-L1/PD-1 treatment, suggesting that the suppressive capacity of the PD-1/PD-L1 axis is dominant over other known co-inhibitory receptors." (PMID 29482595, 2018). "Also correlating were GZMB and FASLG, both necessary for anti-tumor CD8 T cell cytotoxic functionality, PD-1 and LAG3, representing T cell activation and exhaustion, and TAP2, necessary in MHC I antigen presentation." (PMID 29487705, 2018). "As summarized in a recent review addressing the immune checkpoint inhibitors in Tregs, these cells constitutively express immune checkpoints like CTLA-4 but also PD-1, BTLA, LAG-3, and TIM-3, and upregulate inhibitory receptors during activation and at tumor sites." (PMID 30233564, 2018). "Apart from being ligands for LAG-3 and TIM-3, galectins also exert relevant pro-tumor functions." (PMID 30108594, 2018). "Lymphocyte activation gene-3 may synergize with other immune checkpoints, and the combination of anti-LAG-3 and anti-PD-1 resulted in more potent inhibition of murine tumor growth than single treatments." (PMID 30108594, 2018). "Expression of alternative checkpoints such as LAG-3, TIGIT, TIM-3, and ICOS in the tumor microenvironment may also play a key role regarding clinical outcomes and are currently being explored." (PMID 30356816, 2018). "Moreover, LAG3 signaling contributes to CD4+ regulatory T cell suppression of autoimmune responses and CD8+ T cells tolerance to self and tumor antigens." (PMID 29383101, 2017).